TRIM74 (tripartite motif containing 74)
Synonyms: TRIM50C; MGC45440
Tractability: No criterion of Open Targets' tractability assessment is met for any kind of drug.
Gene: Protein-coding gene on chromosome 7 (72,959,485 to 72,969,466, reverse strand). Ensembl gene ENSG00000155428.
Subcellular location (Human Protein Atlas): Cytosol
Gene Ontology:
Molecular function: ubiquitin protein ligase activity; zinc ion binding
Biological process: innate immune response
Cellular component: cytoplasm
Genetic constraint (gnomAD): Loss-of-function variants: 2 observed, 4.13 expected, observed/expected ratio (o/e) 0.48, 90% interval 0.2 to 1.46. That is too few expected variants to judge how well the gene tolerates losing a copy. Missense variants: 13 observed, 54.41 expected, observed/expected ratio (o/e) 0.24, 90% interval 0.16 to 0.38. Synonymous variants: 3 observed, 23.6 expected, observed/expected ratio (o/e) 0.13, 90% interval 0.057 to 0.33.
Homologues: Paralogues in human: TRIM73 (99% identical), TRIM50 (93% identical), MID1 (26% identical), MID2 (26% identical), TRIM27 (26% identical), TRIM72 (24% identical), TRIM11 (23% identical), TRIM68 (23% identical), TRIM22 (23% identical), TRIM39 (23% identical), TRIM4 (22% identical), TRIM41 (22% identical), and 68 more.
Diseases named in the same sentence as TRIM74 in open-access papers:
TRIM74 is named in the same sentence as 2 diseases in open-access papers, as found by Europe PMC text mining. Sharing a sentence is not in itself a finding about the gene and the disease. The quoted sentences say what the papers report.
Williams-Beuren syndrome (1 paper, 2011). "Unequal crossing-over and aberrant homologous recombination between the tandem segments that contain TRIM50, TRIM73, and TRIM74 causes Williams-Beuren syndrome in 1/7,500 to 1/25,000 newborns." (PMID 22144910, 2011).
tumor (1 paper, 2022). "The results showed that stromal tumor-infiltrating lymphocytes (TILs) percent and the expression levels of CD44, B2M, PTPN11, and TRIM74 were associated with DFS in NPC patients." (PMID 36107539, 2022).